MBNL1 (muscleblind like splicing regulator 1)
Diseases named in the same sentence as MBNL1 in open-access papers (continued):
Sharing a sentence is not in itself a finding about the gene and the disease.
leukemia (10 papers, 2017 to 2025). A malignant (clonal) hematologic disorder, involving hematopoietic stem cells and characterized by the presence of primitive or atypical myeloid or lymphoid cells in the bone marrow and the blood. "Together, these results suggest that loss of MBNL1 in MLL rearranged leukemia results in a state analogous to disruption of essential components of the MLL leukemia program, culminating in leukemia cell death." (PMID 32398749, 2020). "Here, the authors show that MBNL1-mediated alternative splicing leads to a specific splicing profile in MLL-rearranged leukaemia and loss or inhibition of MBNL1 impairs leukaemia development in vitro and in vivo." (PMID 32398749, 2020). "Additional research is ongoing to further elucidate the mechanisms underlying MBNL1 dependence in MLL-rearranged leukemia, as well as to further optimize candidate small-molecule inhibitors." (PMID 32398749, 2020). "To characterize the influence of Mbnl1 loss on leukemia-initiating cells in vivo we performed secondary transplantation into irradiated hosts using splenocytes from sick primary mice." (PMID 32398749, 2020). "Intriguingly, these results suggest that at least some targets of MBNL1 are spliced in a tissue-agnostic manner, and that patterns of isoform expression associated with high MBNL1 expression are reversed upon MBNL1 knockdown in leukemia cells." (PMID 32398749, 2020). "Alternately, it is plausible that MBNL1 loss in a transformed cell (i.e., genetic knockdown in leukemia cell lines) may be more deleterious than de novo transformation of an MBNL1-deficient cell, as occurs in the mouse retroviral leukemia model." (PMID 32398749, 2020). "Conversely, MBNL1 overexpression in MLL-rearranged leukemias drives widespread intron removal, altering the expression of key epigenetic modifiers involved in leukemogenesis." (PMID 40305509, 2025). "MBNL1 is the most frequently called oncoprotein target gene across the collection of leukemias we profiled (24/36 samples)." (PMID 39472576, 2024). "MLL-rearranged signatures revealed that muscleblind-like 1 (MBNL1) was one of the most consistently overexpressed genes in MLL-rearranged leukaemia compared to other leukaemias." (PMID 35057823, 2022). "Muscleblind-like splicing regulator 1 (MBNL1), encoded by the MBNL1 gene, is an RNA splicing protein and essential for MLL-rearranged leukemia cell growth." (PMID 33841514, 2021). "We found that MBNL1 loss significantly impairs propagation of murine and human MLL-rearranged leukemia in vitro and in vivo." (PMID 32398749, 2020). "In this report, through a combination of functional genomic studies, pharmacologic inhibition, and comprehensive analysis of alternative splicing we demonstrate that MBNL1 is required in MLL-rearranged leukemia." (PMID 32398749, 2020). "To determine the requirement for MBNL1 in leukemia in vivo, we transduced two primary patient AML samples bearing MLL fusions (one MLL-AF9 and one MLL-AF10) with shMBNL1-64 or a non-targeting (NT) control." (PMID 32398749, 2020). "As a proof of concept, we demonstrate that a small-molecule inhibitor rationally designed against MBNL1 can preferentially kill MLL-rearranged leukemia cells while sparing normal CD34+ hematopoietic stem/progenitor cells." (PMID 32398749, 2020). "Specifically, our data suggest that human MLL-rearranged leukemia cells have increased expression of MBNL1 transcripts that exclude exon 5 which influences nuclear vs cytoplasmic localization of MBNL114,43." (PMID 32398749, 2020). "We then performed short hairpin RNA (shRNA) knockdown studies of MBNL1 in human leukemia cell lines to test its requirement for leukemia cell growth." (PMID 32398749, 2020). "As a complementary means of characterizing the essentiality of MBNL1 in MLL-rearranged leukemia, we used a mouse model of Mbnl1 genetic ablation." (PMID 32398749, 2020).
leukemia (continued). "Analysis of MLL-rearranged signatures reveals that muscleblind-like 1 (MBNL1) is one of the most consistently overexpressed genes in MLL-rearranged leukemia compared to other leukemias." (PMID 32398749, 2020). "We also show that a specific, albeit low potency, inhibitor of MBNL1 preferentially affects MLL-rearranged leukemia cells." (PMID 32398749, 2020). "In these experimental settings, mice transplanted with transformed Mbnl1+/+ cells developed leukemia with a median time of 84 days." (PMID 32398749, 2020). "We subsequently analyzed expression levels of MBNL1 by quantitative RT-PCR (qRT-PCR) in human leukemia cell lines." (PMID 32398749, 2020). "We demonstrate that MBNL1 is an important regulator of alternative splicing events preferentially expressed in MLL-rearranged leukemia and which participate in the MLL-rearranged oncogenic program." (PMID 32398749, 2020). "In examining results of gene expression profiling of MLL leukemias, we identified MBNL1 as one of the most consistently overexpressed genes in this family of leukemia regardless of lineage, even more so than the HOXA cluster genes." (PMID 32398749, 2020). "Collectively, these data show that at least some putative targets of MBNL1 are consistent across different cell types, and that high MBNL1 expression correlates with increased alternative splicing of MBNL1 in MLL-rearranged leukemia." (PMID 32398749, 2020). "To confirm the relevance of MBNL1 expression in MLL-rearranged leukemia, we first compared multiple gene expression studies which identified differentially expressed genes between MLL-rearranged and MLL-wildtype leukemias." (PMID 32398749, 2020). "Similar to our primary transplant experiments, secondary recipients of Mbnl1−/− leukemia cells demonstrated longer leukemia-free survival (65 days) compared to mice secondarily transplanted with Mbnl1+/+ leukemia cells (49 days)." (PMID 32398749, 2020). "Conversely, MBNL1 is consistently overexpressed in MLL-rearranged leukemia." (PMID 40305509, 2025). "Our data suggests that targeting MBNL1 may be a valid therapeutic avenue in the treatment of MLL-rearranged leukemia." (PMID 32398749, 2020). "The alternative splicing regulator MBNL1 is overexpressed in MLL-rearranged leukaemia." (PMID 32398749, 2020). "We speculate that a similar phenomenon might explain the eventual development of leukemia in our Mbnl1−/− mice despite the growth inhibition in our knockdown studies in human cells." (PMID 32398749, 2020). "We sought to identify whether canonical MBNL1 targets exhibit differential patterns of isoform usage across leukemia cells with differing degrees of MBNL1 expression." (PMID 32398749, 2020). "However, mice transplanted with transformed Mbnl1−/− cells demonstrated a significantly prolonged latency and leukemia-free survival of 123 days after transplantation." (PMID 32398749, 2020). "High expression of ARID2, JMJD1C, MBNL1, MEF2C, or RUNX2 alone is associated with at least one indicator of poor prognosis in ALL patients, and CPEB2, MBNL1, RUNX2, and ZEB2 are all specifically overexpressed in MLL-FP leukemias." (PMID 28076791, 2017). "We hypothesize that transformation of Mbnl1−/− cells could conceivably engage alternate oncogenic pathways which eventually allow leukemia cell survival, though this issue of MBNL1 requirement for MLL leukemia initiation versus propagation requires further study." (PMID 32398749, 2020). "As expected, the group of genes we identified as the most frequent KMT2A fusion targets across our collection of samples included several genes that are known to be required for KMT2Ar leukemia, including HOXA9, MEIS1, MEF2C, MBNL1 and JMJD1C25–29." (PMID 34663924, 2021). "MBNL1, a protein involved in alternative splicing, is consistently overexpressed in MLL-rearranged leukemias." (PMID 32398749, 2020).
leukemia (continued). "In comparing the isoform expression profiles of these genes between MLL-wildtype and MLL-rearranged leukemias, we identified shifts in isoform utilization in MLL-rearranged leukemia cell lines which had high MBNL1 expression." (PMID 32398749, 2020). "MBNL1 is a protein involved in alternative splicing, predominantly regulates intron exclusion, and has been found consistently overexpressed in KMT2A-rearranged leukemia." (PMID 36518527, 2022). "In both Mbnl1+/+ and Mbnl1−/− states Mbnl2 and Mbnl3 are stably expressed in mouse leukemia cells, however neither analogue was meaningfully expressed in the human leukemia lines assayed." (PMID 32398749, 2020). "Therefore, one possible explanation for the eventual development of leukemia in our Mbnl1−/− murine model is that Mbnl2 compensates for the absence of Mbnl1, but it is unclear if this compensatory mechanism would necessarily behave similarly in human cells." (PMID 32398749, 2020). "Interestingly, RUNX2, MBNL1, JMJD1C, SENP6, MEF2C, and ZEB2 are also hypomethylated in MLL-FP samples compared to either normal cells or other leukemias (not shown)." (PMID 28076791, 2017).
muscular dystrophies (8 papers, 2010 to 2024). "Consistent with the muscular dystrophy model, Mbnl1 mRNAs levels were typically elevated 2–3 times higher than Celf1 in jejunal and colonic SMC." (PMID 28152551, 2017). "In muscular dystrophies, mutated Dmpk mRNAs containing long CUG repeats induce CELF1 expression, leading to the suppression of MBNL1." (PMID 28152551, 2017). "Three notable exceptions were i) SR-A1 [a.k.a, SCAF1, Serine/Arginine Rich (SR)-related C-terminal domain-associated factor 1] a poorly characterized SR family protein, ii) MBNL1 (Muscleblind-like 1), a RBP known for its role in muscular dystrophy and, (iii) RBM39." (PMID 36477312, 2022). "DMPK functions to protect against muscular dystrophies by balancing the antagonistic activities of two RNA-binding proteins, CUGBP1 (CELF1) and MBNL1, whose dysregulation can lead to abnormal splicing of ion channels, including the voltage-gated calcium channel." (PMID 28152551, 2017).
myotonic dystrophy type 2 (8 papers, 2015 to 2025). Myotonic dystrophy type 2 (MD2), also known as proximal myotonic myopathy, is a very rare genetic multi-system disorder of late childhood or adult-onset characterized by mild myotonia, muscle weakness, and rarely cardiac conduction disorders. "In myotonic dystrophy type 2 models, MBNL1 was also reported to retain CCUG repeat RNA in the nucleus, resulting in the suppression of RAN translation, implying various mechanisms of the effects of RBPs depending on the combination of RBPs and repeat RNA." (PMID 37461319, 2023). "Thus, we propose that the rbFOX proteins, by competing with and reducing the titration of MBNL1 within CCUG RNA foci, may participate to the lesser toxicity of the CCTG repeat expansion in myotonic dystrophy type 2." (PMID 29789616, 2018).
breast carcinoma (6 papers, 2017 to 2025). "It has been recently reported that MBNL1 promotes the mRNA stability of two genes involved in metastasis suppression (DBNL and TACC1) and this effect was linked to breast cancer metastatic colonization, a cancer type where MBNL1 expression was associated to metastasis-free survival." (PMID 28137272, 2017). "In breast cancer, MBNL1 negatively regulates the JNK pathway, thus inhibiting the stemness of breast cancer by modulating RNA splicing." (PMID 38725048, 2024). "The overexpression of tRF‐1‐Ser increased the sphere‐forming ability of breast cancer cells, as evidenced by a significant increase in the number of spheres, which was countered by the overexpression of MBNL1 and the use of JNK‐IN‐8." (PMID 38725048, 2024). "Protein MBNL1, which was co-acted by all differentially expressed lncRNAs, was found in human breast cancer and colorectal cancer." (PMID 29383134, 2017). "To understand how tRF‐1‐Ser and MBNL1 interact and regulate biological functions, we analysed transcriptome data from TCGA containing 1231 breast cancer cases, categorised based on the average TPM values of MBNL1 into high‐ and low‐expression groups (MBNL1_high and MBNL1_low, respectively)." (PMID 38725048, 2024). "Furthermore, tRF‐1‐Ser enhanced breast cancer stemness, which can be reversed by the MBNL1 overexpression or JNK‐IN‐8 application." (PMID 38725048, 2024). "In malignant tumours, including breast cancer, MBNL1 expression is often reduced." (PMID 38725048, 2024). "Therefore, tRF‐1‐Ser can enhance the stemness of breast cancer cells by inhibiting the negative regulation of JNK activity by MBNL1." (PMID 38725048, 2024). "Considering the roles of MBNL1 and JNK‐in BCSCs, we conducted flow cytometry and sphere formation assays to study the effects of tRF‐1‐Ser on breast cancer stemness." (PMID 38725048, 2024). "Since TCEAL2 and MBNL1 have been reported to be potential therapeutic targets in SCLC and breast cancer respectively, their translation values in GC are worthy of further investigation." (PMID 35421923, 2022). "Additionally, it has been reported that MBNL1 suppresses the JNK pathway, which in turn reduces the stemness of breast cancer cells." (PMID 38725048, 2024).
cardiac arrhythmia (6 papers, 2015 to 2023). Any disturbances of the normal rhythmic beating of the heart or MYOCARDIAL CONTRACTION. "In parallel, analyses of Mbnl1 mutant mice and evidence that misregulation of MBNL1-splice target gene SCN5A encoding a cardiac sodium channel leads to cardiac arrhythmia and conduction delay, indicate that Mbnl1 contributes to DM1 heart phenotypes." (PMID 31829940, 2019). "Our study shows that (i) the tri-cellular cardiac microtissues promote post-natal SCN5A isoform switch in hiPSC-CMs, (ii) adult splicing of SCN5A is driven by MBNL1 in these tissues, and (iii) this model can be used for examining post-natal cardiac arrhythmias due to mutations in the exon 6B." (PMID 35394010, 2023).
cardiac hypertrophy (5 papers, 2015 to 2024). "This article focuses on the interaction between MBNL1 and Myocardin and their underlying molecular mechanism in regulating myocardial hypertrophy." (PMID 33295096, 2021). "Restoring MBNL2 to near wild type levels in Mbnl1-null mice by removal of one Mbnl2 allele was sufficient to induce atrial dilation, ventricular hypertrophy, and conduction defects." (PMID 26472242, 2015). "The concurrent manifestation of conduction defects, ventricular hypertrophy and histological abnormalities may therefore serve to increase the predisposition to sudden cardiac death with Mbnl1 depletion." (PMID 25761764, 2015). "The relationship between TRA and the reduction of cardiac hypertrophy is also supported by our finding that the expression of Mbnl1 and Ptpb1 was reduced in TRA-treated SHR rats." (PMID 39355349, 2024). "By analysing the data in the GEO database (GSE129090), we found that MBNL1 was highly expressed myocardial hypertrophy samples." (PMID 33295096, 2021). "Our findings reveal a new function of MBNL1 in cardiac hypertrophy and the molecular network of the post‐transcriptional regulation of Myocardin." (PMID 33295096, 2021). "MBNL1 can up‐regulate the stability of Myocardin mRNA, resulting in the promotion of myocardial hypertrophy and myocardial fibrosis." (PMID 33295096, 2021). "MBNL1 promoted ISO‐induced cardiac hypertrophy and fibrosis by stabilizing Myocardin mRNA in vivo and in vitro." (PMID 33295096, 2021). "Here, we confirmed that MBNL1 directly binds to Myocardin mRNA to inhibit the degradation of Myocardin mRNA, thereby regulating the occurrence and development of myocardial hypertrophy." (PMID 33295096, 2021). "In this study, we confirmed that MBNL1 can increase the expression of Myocardin by inhibiting the degradation of Myocardin mRNA, which implicate myocardial hypertrophy and its subsequent pathophysiology." (PMID 33295096, 2021). "When cardiac hypertrophy occurred, the overexpression of Myocardin also increased MBNL1 protein levels, which further strengthened the stability of Myocardin mRNA; this in turn maintained the increased abundance of Mycoardin and promoted myocardial remodelling." (PMID 33295096, 2021). "In this study, we explored the relationship between MBNL1 abundance in peripheral blood and cardiac hypertrophy which may provide a new direction for the early diagnosis of myocardial hypertrophy in the future." (PMID 33295096, 2021). "The level of MBNL1 was significantly higher in myocardial hypertrophy mice than in normal mice." (PMID 33295096, 2021). "Recently, it has been described that Mbnl1 mouse mutants develop cardiac problems prominent in DM1 (cardiac hypertrophy, interstitial fibrosis, alterations in transcript splicing), which suggests a key role of Mbnl1 in the initiation of cardiac problems in DM1." (PMID 31717488, 2019). "To date, the relationship between MBNL1 and myocardial hypertrophy remains unclear." (PMID 33295096, 2021). "Then, the changes in the expression of two cardiac hypertrophy‐specific genes, namely ACTN2 and ANP, in the primary myocardium with overexpressed or silenced MBNL1 were detected using realtime PCR and Western blotting." (PMID 33295096, 2021). "In this study, we observed the high expression of MBNL1 in cardiac tissue and peripheral blood of an isoproterenol (ISO)‐induced cardiac hypertrophy mouse model." (PMID 33295096, 2021). "If ASOs or other small molecular inhibitors are designed for the combination of MBNL1/Myocardin and MBNL1/TNF‐α, it may be possible to inhibit cardiac hypertrophy and prevent the apoptosis of cardiomyocytes." (PMID 33295096, 2021). "Phalloidin staining confirmed that MBNL1 could not effectively induce myocardial hypertrophy with Myocardin knockdown." (PMID 33295096, 2021).
cardiac hypertrophy (continued). "Mbnl1 depletion in 129 sv mice results in QRS and QTc widening, STc shortening, bundle blocks, diminished R wave amplitudes and SA node dysfunction in conjunction with cardiac hypertrophy, fibrosis, multi-focal myofibrillar death, calcification and sudden death." (PMID 25761764, 2015).
cataract (5 papers, 2010 to 2022). Partial or complete opacity of the crystalline lens of one or both eyes that decreases visual acuity and eventually results in blindness. "Mbnl1 knockout adults develop muscle myotonia and myopathy, subcapsular dust-like cataracts, and alternative splicing changes characteristic of DM1, while compound loss of MBNL1 and MBNL2 is required for the onset of severe muscle wasting." (PMID 32086392, 2020). "Dmpk−/− mice display muscle weakness and heart disease, Six5−/− mice display cataracts and heart disease and Mbnl1−/− mice display skeletal myotonia, muscle weakness, cataracts and possibly heart disease." (PMID 20360842, 2010).
colorectal cancer (4 papers, 2017 to 2022). A primary or metastatic malignant neoplasm that affects the colon or rectum. "An existing research observed that lncRNA MBNL1 was bound with C allelic pre-miR-1307, which led to a reduced expression of miR-1307-3p, thus increasing the susceptibility to colorectal cancer." (PMID 31113460, 2019). "In colorectal cancer, MBNL1 destabilizes Snail and inhibits the epithelial‐to‐mesenchymal transition and metastasis of tumour cells." (PMID 34890108, 2022). "MBNL1 plays a vital role in the initiation of colorectal cancer (CRC) by reducing the expression of microRNAs (miRNAs/miRs)." (PMID 31113460, 2019). "Even a report has indicated that rs7911488 C-allelic pre-miR-1307 binds to MBNL1 and infers with Dicer processing, and then leads to the decreased miR-1307 and increased Bcl-2 expression, thus representing an important process in the initiation of colorectal cancer." (PMID 28086946, 2017).